RN7SKP250 (RN7SK pseudogene 250)
Gene: Miscellaneous RNA gene on chromosome 12 (109,662,863 to 109,663,183, reverse strand). Ensembl gene ENSG00000200794.
Homologues: Paralogues in human: RN7SKP180 (74% identical), 7SK (74% identical), RN7SKP71 (74% identical), RN7SKP189 (74% identical), RN7SKP204 (74% identical), RN7SKP255 (74% identical), RN7SKP170 (73% identical), RN7SKP133 (73% identical), RN7SKP176 (73% identical), RN7SKP203 (73% identical), RN7SKP211 (73% identical), RN7SKP217 (73% identical), and 284 more.